IGF1 (insulin like growth factor 1)
Diseases named in the same sentence as IGF1 in open-access papers (continued):
Sharing a sentence is not in itself a finding about the gene and the disease.
pancreatic cancer (continued). "Indeed, inhibition of IGF1/AKT signalling alongside c-MYC or KRAS inhibition increased pancreatic cancer cell clearance and delayed tumour recurrence in these mice." (PMID 37608096, 2023). "However, the literature on IGF-1 in pancreatic cancer is inconsistent, with some studies confirming high levels in both CP and PDAC, while others do not." (PMID 37373743, 2023). "Observed significant association between pancreatic cancer risk and polymorphisms in IGF1, IGF1R & IGFBP1 but SNPs in IGFBP5 were not significant." (PMID 36465383, 2022). "Besides inhibiting SIRT1 and PARP1, NAM has shown to inhibit the oncogenic KRAS/AKT pathway in skin and pancreatic cancers, modulate the expression of Myc oncogene in bladder cancer, and suppress IGF-1 in HCC." (PMID 32245130, 2020). "We hypothesized that CR would inhibit pancreatic tumor growth through modulation of IGF-1-stimulated NF-κB activation and protumorigenic gene expression." (PMID 24804677, 2014). "IGF-1R and IGF-1 are overexpressed in human pancreatic tumors." (PMID 22570653, 2012). "In fact, measuring IGF-1 levels in bile could help distinguish extrahepatic CC from pancreatic cancer or benign biliary stenosis and blocking estrogen, IGF-1, and VEGF receptors could be crucial to arrest CC cell proliferation." (PMID 21994887, 2012). "Since EGF, TGF-alpha and IGF-1 are considered to play an important role in the proliferation of pancreatic cancer cells, we studied the effects of tyrphostins on the growth of three human pancreatic cancer cell lines (MiaPaCa-2, Panc-1 and CAV)." (PMID 8260363, 1993). "Together, these findings demonstrate that PCDH1 knockdown suppresses pancreatic cancer cell migration, whereas IGF-1 stimulation counteracts this effect, suggesting that PCDH1 may regulate cell motility at least in part through the IGF-1–associated signaling pathway." (PMID 41602375, 2026). "Increased expression of IGF-1 and IGF1R in PDAC is closely associated with unfavorable clinical outcomes, with elevated levels correlating with poor survival rates and higher tumor grades, establishing them as prognostic indicators for pancreatic cancer patients." (PMID 39087024, 2024). "Moreover, C1QB levels in pancreatic cancer may serve as a predictor of disease given its role in the regulation of IGF-1/IGF-1R signaling, which plays a role in the cell spreading, and in the induction of hepatic metastasis." (PMID 37628784, 2023). "This is rather surprising, since high serum levels of IGFBP3 are supposed to inhibit IGF1, thereby reducing the availability of a relevant growth factor for PDAC and the relative levels of IGFBP3 and IGF in serum have been associated with risk of pancreatic cancer, at least in some studies." (PMID 27539223, 2016). "Excess IGFBP5 has been shown to regulate myotube differentiation probably via modulation of IGF-2 signaling, however, whether IGFBP-3, which predominantly binds to IGF-1 and exhibits the greatest induction in pancreatic tumors, affects myogenesis is largely unknown." (PMID 26975989, 2016). "Therefore, we stratified our analysis by circulating C-peptide concentration to evaluate whether the association between IGF-1 and IGFBP-3, and pancreatic cancer was different in individuals with high or low C-peptide levels." (PMID 22315049, 2012). "In pancreatic cancer, IGF-IR, STAT3, HIF-1α, IL-6, IGF-1, amongst others, have been described to be active and linked to the HSP90 pathways." (PMID 36966394, 2023). "Our previous study reported that insulin/IGF-1 stimulates Complement component 1, q subcomponent binding protein (C1QBP), to mediate anti-apoptosis and invasion of pancreatic cancer." (PMID 35252207, 2022). "In pancreatic cancer, RON has been shown to interact with insulin-like growth factor-1 (IGFR-1) and becomes activated by IGF1-R after IGF1 stimulation." (PMID 35454943, 2022).
pancreatic cancer (continued). "A previous study supported the use of a combination of two markers, IGF-1 and albumin, with CA19-9 to increase the sensitivity to 93.6% in pancreatic cancer." (PMID 36555927, 2022). "Expression levels of IGF-1 and VEGF in the bile and serum of extrahepatic cholangiocarcinoma, pancreatic cancer, and benign biliary abnormalities were measured to evaluate their role as a tumor marker." (PMID 36389727, 2022). "For instance, IGF-1 activates the IGF-1R/AKT/mTOR survival pathway in CRC, and CXCL-12 promotes EMT and invasion in pancreatic cancer." (PMID 33553157, 2020). "Furthermore, levels of IGF-1 approximating those found in overweight or obese mice increase NF-κB nuclear translocation, DNA binding, transcriptional activation, and downstream gene expression of inflammation and protumorigenic genes in Panc02 pancreatic cancer cells." (PMID 24804677, 2014). "The focus of this brief article is on the central role of the mechanistic/mammalian target of rapamycin (mTOR) in mediating insulin/IGF-1 and G protein-coupled receptor (GPCR) signaling leading to proliferation of pancreatic cancer cells." (PMID 25295009, 2014). "Klotho was shown to exert an inhibitory effect on the insulin-like growth factor-1 (IGF-1) pathway both in human beast cancer cells and pancreatic cancer cells." (PMID 23437382, 2013). "Insulin-like growth factor 1 (IGF-1) and IGF-1 receptor are highly expressed in pancreatic cancer cells." (PMID 22920886, 2012). "IGF-1 exposure decreased phosphorylation and inactivation of PTEN and activation of PI3K, AKT, and the NF-κB pathway in a number of pancreatic cancer cell lines resulting in their enhanced proliferation and invasiveness." (PMID 22570653, 2012). "IGF-1 and its receptor IGF-1R play a major role in proliferation, invasive potential, and metastatic behavior of pancreatic cancer cells." (PMID 22570653, 2012). "A multivariate analysis of pancreatic cancer divided the patients into two groups based on their serum concentration of VEGF, bFGF, and IGF-1: resectable and unresectable." (PMID 24212642, 2011). "We examined the effects of SS-14 and its analogue RC-160 on the in vitro growth of two human pancreatic cancer cell lines MiaPaCa-2 and Panc-1 stimulated with epidermal growth factor (EGF) or insulin-like growth factor 1 (IGF-1)." (PMID 1355659, 1992). "Furthermore, through the IGF-1/IGF-1R signaling pathway, p32 mediates pancreatic cancer's hepatic metastasis." (PMID 38169635, 2024). "More specifically, in a study of pancreatic cancer, tumor cells harboring the mutant KRASG12D communicated with CAFs via sonic hedgehog signaling, which stimulated the production of insulin-like growth factor 1 (IGF-1) in CAFs; in turn, reciprocal signaling affected tumor cell proliferation." (PMID 37173977, 2023). "In pancreatic cancer, the ablation of the oncogenic drivers mutant KRAS and c-MYC induces a dormant state, allowing the survival of a few residual cancer cells, which rely on autocrine IGF1/AKT as an adaptive mechanism." (PMID 35158815, 2022). "In pancreatic cancer, the ablation of the oncogenic drivers mutant KRAS and c-MYC induces a dormant state, allowing the survival of a few residual cancer cells that rely on autocrine IGF1/AKT as an adaptive mechanism." (PMID 35158815, 2022). "IGF-1 and HRG by targeting the PI3K/AKT pathway could reduce pancreatic cancer cell sensitivity to gemcitabine or paclitaxel." (PMID 33768092, 2021). "Furthermore, increased amounts of insulin, insulin-like growth factor-1 (IGF-1) and IGF-binding proteins are detected in the sera and tissues of pancreatic cancer patients and promote tumour growth, metastasis and chemoresistance." (PMID 33536560, 2021). "Nonetheless, it is apparent that miR-29a modulates extracellular IGF-1/IGF-1R signaling in PSCs, and intracellular NRAS expression in pancreatic cancer cells, which indicates a functional role of the molecule in tumor-stromal crosstalk via insulin/IRF -RAS/MAPK signaling mechanism in PDAC." (PMID 32660466, 2020).
pancreatic cancer (continued). "Since both the ERK and PI3K pathways are effectors of KRAS, activating mutations of KRAS reinforce the crosstalk between insulin/IGF-1 receptor and GPCR signaling systems, thereby increasing the robustness of the network induced by insulin/IGF-1 and GPCR agonists in pancreatic cancer cells." (PMID 25295009, 2014). "This article highlights the central role of the mechanistic target of rapamycin (mTOR) in mediating crosstalk between insulin/IGF-1 and GPCR signaling in pancreatic cancer cells and proposes strategies, including the use of metformin, to target this signaling system in PDAC cells." (PMID 25295009, 2014). "Adversely, IGF-1 is not directly mutagenic but a potent mitogen and cancer risk; for example, prospective blood samples show elevated IGF-1 levels in individuals later diagnosed with prostate and pancreatic cancer." (PMID 34695806, 2021). "Furthermore, CAF-derived IGF-1 and IGF-2 induce CT resistance in pancreatic cancer." (PMID 33553157, 2020). "However, we realized that glucose, insulin and IGF-1 did not affect the growth of Panc02-Luc-ZsGreen cells even at high concentrations, although these have been reported to influence the proliferation of human pancreatic cancer cells." (PMID 33536560, 2021). "In pancreatic cancer cells, MAP4K3 knockdown cells failed to phosphorylate PKCθ, and inhibition of PKCθ activity suppressed insulin-like growth factor-1-mediated cell growth and viability, indicating that the MAP4K3/PKCθ axis may be a therapeutic target for pancreatic cancer." (PMID 36358843, 2022).
hepatocellular carcinoma (130 papers, 2006 to 2026). A malignant tumor that arises from hepatocytes. "The reduction in IGF-1 production occurs primarily in chronic liver diseases, e.g., viral-associated chronic hepatitis, and hepatocellular carcinoma (HCC)." (PMID 34208601, 2021). "After controlling for some data (hepatitis infection, BMI, smoking and alcohol abuse), a higher molar difference of IGFBP3 and IGF1 was connected with a decreased hepatoma risk, more than IGFBP3 alone." (PMID 29702590, 2018). "In hepatocellular carcinoma, the treatment of insulin-like growth factor 1 promoted CK2-mediated CLOCK S106 phosphorylation, which consequentially disrupts the CLOCK-BMAL1 heterodimer and suppresses the expression of its downstream genes." (PMID 39827153, 2025). "EGCG can also attenuate the growth of hepatocellular carcinoma cells by inhibiting the IGF-1/IGF-1R axis and ERK, AKT, STAT3, and GSK3β signals." (PMID 40218859, 2025). "Despite its role in liver steatosis, IGF-1 has a key role in fibrinogenesis, cirrhosis, and hepatocellular carcinoma development through stimulation of liver degeneration and tissue repair." (PMID 39781288, 2025). "In fact, it has been shown that hepatoma cells overexpress IGF-1 and insulin receptor substrate-1, suggesting their importance in HCC development." (PMID 36831004, 2023). "Relationship between hepatic expression of GHR/STAT5/IGF-1 signaling pathway and clinico-pathological features of the tumor in cirrhotic patients with hepatocellular carcinoma." (PMID 36374927, 2022). "The aim of this study was to evaluate the hepatic expression of GHR/STAT5/IGF-1 signaling pathway in hepatocellular carcinoma (HCC) patients and to correlate the results with the clinico-pathological features and disease outcome." (PMID 36374927, 2022). "IGF-1 induces the growth and metastasis of hepatocellular carcinoma by inhibiting protease-induced cathepsin B degradation." (PMID 35203722, 2022). "It has been shown that IGF1 promoted metastasis of melanoma cells and also promoted migration and invasion of hepatocellular carcinoma cells through upregulating the expression of EGR1." (PMID 35479581, 2022). "IGF-1 has an inhibitory effect on lipolytic enzyme lipoprotein lipase which prevents the virus cell entry in hepatoma cells." (PMID 36374927, 2022). "A previous study demonstrated that IGF-1 conferred sorafenib resistance to hepatocellular carcinoma cells by regulating RAS/RAF/ERK signaling pathways." (PMID 34340705, 2021). "Insulin-like growth factor 1 (IGF1) dramatically increased DNMT1 expression in hepatocellular carcinomas (HCCs) via Akt/GSK-3β signaling pathway activation." (PMID 34162834, 2021). "miR-190b is significantly upregulated in hepatocellular carcinoma cells and interacts with the 3′-untranslated region of IGF-1." (PMID 32908867, 2020). "Knockdown of Cav1 reduces e.g. IGF1 signaling in H9C2 rat cardiomyoblasts whereas Cav1 overexpression significantly increases IGF1-induced internalization of IGF-1R in human hepatocellular carcinoma cells." (PMID 32458278, 2020). "For instance, overexpression of miR-342-3p inhibits cell proliferation in hepatocellular carcinoma through the inhibition of insulin-like growth factor 1-mediated Warburg effect." (PMID 32025219, 2020). "STAT5 has been recently found to co-operate with insulin-like growth factor 1 (IGF-1) to enhance EMT in hepatocellular carcinoma." (PMID 33255651, 2020). "Overnight serum starvation decreases the IP7 level in mouse embryonic fibroblast (MEF) or human hepatocellular carcinoma (HepG2) cells, which is restored by exposure to insulin-like growth factor-1 (IGF-1) or insulin." (PMID 32204420, 2020). "Our observations corroborate previous studies showing the participation of IGF-1 in tumor cell migration in multiple models of myeloma, hepatocellular carcinoma and melanoma." (PMID 32899449, 2020).
hepatocellular carcinoma (continued). "It was also discovered, by in vitro studies, that the dominating pathways, activated by IGF1 in hepatocytes and hepatoma cell lines, involve the PI3K/Akt, as well as signal transducer and activator protein family (STAT), signalling pathways." (PMID 29702590, 2018). "A previous study has reported that development of hepatocellular carcinoma (HCC) was accompanied by an conspicuous reduction in serum IGF-1 levels and an overexpression of miR-190b." (PMID 30648107, 2018). "Insulin-like growth factor-1 (IGF1) is correlated with proliferation and migration of hepatocellular carcinoma." (PMID 29312626, 2017). "Previous studies have supported an association between serum insulin-like growth factor-1 (IGF1) and IGF-binding protein 3 (IGFBP3) levels and hepatocellular carcinoma (HCC), but the results were inaccurate." (PMID 29113370, 2017). "Another bona fide miR-190 target is IGF-1, which is significantly reduced in serum of patients with hepatocellular carcinoma." (PMID 27223464, 2016). "In hepatocellular carcinoma, miR-190b is effective in the suppression of IGF-1, and it is reported to play a critical role in fish osmoregulation." (PMID 26301415, 2015). "Namely, low levels of insulin and insulin growth factor (IGF)-1 in CR serum mediate a partial protection against hydrogen peroxide in rat hepatoma cells." (PMID 25711920, 2015). "Previous study reported that development of hepatocellular carcinoma (HCC) was accompanied by a significant reduction in serum IGF-1 levels." (PMID 24586785, 2014). "According to our data, human hepatoma cells use IGF1 to prevent intercellular exosomal transfer of miR-122 to ensure its own proliferation by preventing expression of growth retarding miR-122 in neighbouring cells." (PMID 24813441, 2014). "Our focus on insulin and IGF-1 signaling pathways stemmed from earlier studies demonstrating over-expression of AAH in hepatocellular carcinoma cells and in transgenic mice that over-express IRS-1." (PMID 17156427, 2006). "In this regard, it is noteworthy that in hepatocellular carcinoma cells, IRS-1 over-expression is associated with increased insulin and IGF-1-stimulated growth and survival signaling, in addition to AAH over-expression relative to the normal liver." (PMID 17156427, 2006). "Decreased levels of IGF-1 have been detected in hepatocellular carcinoma tissues." (PMID 41153350, 2025). "Moreover, miR-28-5p was identified as a potential biomarker of hepatocellular carcinoma, while IGF-1 and miR-28-5p had an inverse relation in cancer cells." (PMID 41153350, 2025). "Insulin‐like growth factor‐1 (IGF‐1) is a peptide growth factor produced mainly by the liver, which can horizontally reflect liver function, and its expression is downregulated in chronic liver disease and hepatocellular carcinoma." (PMID 38842135, 2024). "When Fao rat hepatoma cells, human HepG2 hepatoma cells, and rat primary hepatocytes were cultured in serum-free complete medium (Full medium) or amino acid-depleted medium (Zero medium) for 24 h, Igf1 mRNA expression was much lower in the Zero medium." (PMID 35563827, 2022). "For instance, Sorafenib could inhibit macrophage-induced growth of hepatoma cells by disrupting IGF1 secretion." (PMID 35196258, 2022). "Moreover, additional studies have shown that IGF1 expression is upregulated in other cancers (including hepatocellular carcinoma), predicting a lower 10-year survival rate." (PMID 34551673, 2021). "In addition, medications such as sorafenib have also demonstrated ability to reduce the expression of IGF-1 by M2 macrophages as well as the following IGF-1-driven hepatocellular carcinoma growth in a preclinical study." (PMID 32512898, 2020). "In addition, both insulin and insulin-like growth factor-1 (IGF-1) stimulation activate the Wnt signaling pathway in the hepatoma cells." (PMID 30866603, 2019).